BNIP3 (BCL2 interacting protein 3)
Diseases named in the same sentence as BNIP3 in open-access papers (continued):
Sharing a sentence is not in itself a finding about the gene and the disease.
nasal polyps (2 papers, 2022 to 2025). "Western blot analysis of mitochondrial proteins also revealed significantly reduced levels of PINK1, parkin, BNIP3, and FUNDC1 in the nasal polyps of patients with eCRSwNP (P < 0.001, 0.004, 0.002, and 0.013, respectively), compared with control tissues." (PMID 35747690, 2022). "The expression of PINK1, BNIP3, and FUNDC1 proteins was also decreased in the nasal polyps of patients with noeCRSwNP." (PMID 35747690, 2022). "Beclin 1, PINK1, BNIP3, and FUNDC1 levels were significantly reduced in the nasal polyps of patients with eCRSwNP or noeCRSwNP." (PMID 35747690, 2022). "In this study, we demonstrated that the expression of PINK1, parkin, BNIP3, and FUNDC1 proteins was markedly decreased in the nasal polyps of patients with eCRSwNP, compared with control tissues." (PMID 35747690, 2022). "Western blot analysis of total proteins revealed reduced levels of PINK1, parkin, BNIP3, and FUNDC1 in the nasal polyps of patients with eCRSwNP (P = 0.002, <0.001, 0.001, and <0.001, respectively) or noeCRSwNP (P = 0.002, <0.001, <0.001, and <0.001, respectively), compared with control tissues." (PMID 35747690, 2022).
retinal degeneration (2 papers, 2024 to 2026). Degeneration of the retina. "In this aspect, we previously demonstrated that the HIF-1α/BNIP3 pathway could be one of the promising therapeutic targets in retinal degeneration in a murine model of retinal ischemia/reperfusion injury and unilateral common carotid artery occlusion, or a 661W photoreceptor cell line." (PMID 38536853, 2024).
retinal ischemia (2 papers, 2021 to 2024). A ischemic disease that involves the retina. "Previously, we demonstrated HIF-1α/BNIP3 pathway could be associated with inner retinal degeneration in a murine model of retinal ischemia/reperfusion injury by a transient induction of high IOP." (PMID 35005021, 2021).
rheumatoid arthritis (2 papers, 2022 to 2024). A chronic, systemic autoimmune disorder characterized by inflammation in the synovial membranes and articular surfaces. "In rheumatoid arthritis (RA) patients, the activation of fibroblast-like synoviocytes (FLS) under hypoxic conditions involves BNIP3-mediated mitophagy." (PMID 39416788, 2024).
schizophrenia (2 papers, 2021 to 2026). A major psychotic disorder characterized by abnormalities in the perception or expression of reality. "Collectively, this study provides the first evidence that the ERVWE1/miR-27b-3p/BNIP3 axis contributes to mitochondrial dysfunction and neuronal apoptosis in schizophrenia." (PMID 41754588, 2026). "Bioinformatic analysis of the public dataset GSE53987 revealed significantly elevated BNIP3 expression in the brain tissues of patients with schizophrenia, accompanied by enrichment of mitochondria-related pathways." (PMID 41754588, 2026). "Consistently, BNIP3 expression was also increased in the peripheral blood of schizophrenia patients and positively correlated with ERVWE1 levels." (PMID 41754588, 2026).
Skeletal muscle atrophy (2 papers, 2023 to 2024). The presence of skeletal muscular atrophy (which is also known as amyotrophy). "Their target genes, including FBXO32 (also known as MAFbx/Atrogin-1), TRIM63 (also known as MuRF1), CTSL, and BNIP3, are commonly upregulated in various models of skeletal muscle atrophy, and their upregulation accelerates protein degradation." (PMID 38540418, 2024). "Our findings suggested that BNIP3-denpendent mitophagy was sustained activated at the early stages of remobilization, and it might contribute to the worsening of skeletal muscle atrophy." (PMID 37542244, 2023).
Sleep apnea (2 papers, 2020 to 2025). An intermittent cessation of airflow at the mouth and nose during sleep is known as sleep apnea. "A study in a mouse model of sleep apnea revealed that pinocembrin mitigates neuroinflammation by triggering BNIP3-dependent mitophagy via the JNK-ERK signaling cascade." (PMID 40333577, 2025).
steatosis (2 papers, 2024 to 2025). Increased lipid within the cytoplasm of cells. "Consistent with the in vivo results, there was less steatosis in the BNIP3 + L-Phe group than in the L-Phe group (p < 0.05)." (PMID 40588730, 2025). "BNIP3 also exerts a protective effect on MASLD pathogenesis, and loss of BNIP3 results in impaired FAO and increased steatosis in animal models of MASLD53." (PMID 39100919, 2024).
systolic heart failure (2 papers, 2018 to 2019). Heart failure caused by abnormal myocardial contraction during systole leading to defective cardiac emptying. "BNIP3 monomer expression significantly increases in PE-stressed cardiomyocytes and in constitutively active FOXO3a expressing cardiomyocytes in vitro and in animal models of myocardial remodeling and systolic dysfunction, in vivo, as well as in human systolic heart failure." (PMID 31163678, 2019).
trichomoniasis (2 papers, 2023 to 2024). An infection that is caused by Trichomonas. "Moreover, AP65/BNIP3 interaction causes T. vaginalis to adhere to host cells and become pathogenic, and this protein is introduced as a basis for preventing and treating trichomoniasis." (PMID 38556882, 2024). "In addition, the AP65/BNIP3 interaction causes T. vaginalis to adhere to host cells and become pathogenic, and this protein is being introduced as a basis for the prevention and treatment of trichomoniasis." (PMID 38556882, 2024). "Our study showed that the interaction between TvAP33 and BNIP3 mediated the adhesion and pathogenicity of T. vaginalis to host cells, providing a basis for searching for drug targets for T. vaginalis as well as new ideas for the prevention and treatment of trichomoniasis." (PMID 37344876, 2023).
tuberculosis (2 papers, 2023 to 2025). A chronic, recurrent infection caused by the bacterium Mycobacterium tuberculosis. "Therefore, BNIP3 might be a novel therapeutic target for tuberculosis treatment." (PMID 37649112, 2023).
ulcerative colitis (2 papers, 2023 to 2024). An inflammatory bowel disease involving the mucosal surface of the large intestine and rectum. "NR1D1 regulates BNIP3-mediated mitophagy in ulcerative colitis to alleviate colitis symptoms." (PMID 38732079, 2024).
Acute hepatitis (1 paper, 2011). Acute hepatic injury resulting from inflammation typically accompanied by increased serum alanine transaminase activity. "We have reported that Con A induced an acute hepatitis via a BNIP3 dependent mitochondria autophagic pathway in hepatocytes." (PMID 22163006, 2011).
adenovirus infection (1 paper, 2019). "Persistent adenovirus infection of B-lymphocytes has been shown to significantly down-regulate several cellular genes (BBS9, BNIP3, BTG3, CXADR, SLFN11, and SPARCL -), however, none are reported to obviously function in the regulation of metabolism." (PMID 31864392, 2019).
Alpers syndrome (1 paper, 2025). A cerebral degeneration that results in progressive degeneration of grey matter in the cerebrum and has_symptom convulsions. "Intriguingly, the disparities in OXPHOS protein deficiencies between the Alpers’ syndrome and adult PMD patient groups were mirrored by an increased expression of the autophagy- and mitophagy-related proteins LC3B and BNIP3 within Purkinje cells of patients with Alpers’ syndrome." (PMID 40445405, 2025).
bladder cancer (1 paper, 2012). "In addition, mutant Ras was found together with overexpression of BNIP3 and increased autophagy levels in the tumors of bladder cancer patients, suggesting that modulation of BNIP3-linked autophagy may be of therapeutic interest." (PMID 24710477, 2012).
brain cancer (1 paper, 2025). A primary or metastatic malignant neoplasm affecting the brain. "In particular, STAT3 phosphorylation upregulates BNIP3 expression and contributes to the survival of brain cancer cells via autophagy." (PMID 40021617, 2025).
cardiac arrest (1 paper, 2024). Cessation of breathing and/or cardiac function. "However, 2 days after cardiac arrest, the expression of the BNIP3 gene was below the control value, and after 7 and 30 days its expression increased significantly above the control value." (PMID 38279289, 2024). "However, BNIP3 gene expression after cardiac arrest was below control values for 2–30 days of observation." (PMID 38279289, 2024). "However, mitophagy (BNIP3) gene expression 2 days after ischemia in CA1 was above the control value, and on days 7 and 30 after cardiac arrest, it was within the control range." (PMID 38279289, 2024).
cerebrovascular diseases (1 paper, 2018). "Given the diverse roles of Bnip3 splice variants regulating mitochondrial function, autophagy, and cell growth, dysregulation of this genetic pathway may have broad implications involving ischemic cardiovascular and cerebrovascular diseases, as well as cancer biology." (PMID 30275982, 2018).
co-infection (1 paper, 2012). "Because the co-expression of Mieap, NIX, and BNIP3 by co-infection with Ad-Mieap, Ad-BNIP3, and Ad-NIX at a MOI of 5 resulted in the dramatic reduction of MMP, we reasoned that cell death must be induced under this condition." (PMID 22292033, 2012). "Additionally, the co-infection with Ad-BNIP3 and Ad-Mieap α or Ad-Mieap β or the co-infection with Ad-NIX and Ad-Mieap α or Ad-Mieap β did not enhance the effect of the expression of BNIP3, NIX or Mieap alone." (PMID 22292033, 2012).
cyst (1 paper, 2015). A sac-like closed membranous structure that may be empty or contain fluid or amorphous material. "In addition, ANO6 was highly expressed in rounded apoptotic epithelial cells characterized by strong expression of the pro-apoptotic protein BNIP3, supporting the hypothesis of a functional role of ANO6 in apoptosis of cyst-lining epithelial cells." (PMID 26448322, 2015).
diastolic heart failure (1 paper, 2024). Heart failure caused by abnormal myocardial relaxation during diastole leading to defective cardiac filling. "Conversely, BNIP3 has also been proposed as a potential therapeutic target for the treatment of diastolic heart failure." (PMID 39335874, 2024).
Dominant optic atrophy (1 paper, 2024). "Interestingly, past studies have implicated BNIP3 in the progression of Dominant optic atrophy (DOA), a disease that arises due to mutations in OPA1, an important fusion protein in the mitochondrial dynamics." (PMID 38030595, 2024).
endotoxemia (1 paper, 2021). "A substantial increase in caspase-3 and BNIP-3 expression levels and the appearance of TUNEL-positive apoptotic nuclei in diaphragm muscle fibers were observed in mice with endotoxemia treated with VT = 10 mL/kg compared with mice in the other MV treatment groups and the control group." (PMID 33567713, 2021).
fibrosarcoma (1 paper, 2021). A malignant mesenchymal fibroblastic neoplasm affecting the soft tissue and bone. "BNIP3 and NIX mRNA and BNIP3 protein are induced by hypoxic environment in a wide range of human epithelial, endothelial, and macrophage cell lines but not in fibrosarcoma or lymphocyte cell lines." (PMID 34067882, 2021).
gastric adenocarcinoma (1 paper, 2014). "The data demonstrated that BNIP3 levels significantly decreased in patients with low grade differentiated gastric adenocarcinoma." (PMID 24527069, 2014). "Additionally, protein levels of the apoptosis inducer, BNIP3, decreased in the low grade differentiated gastric adenocarcinoma cells." (PMID 24527069, 2014). "Here, the apoptotic events are characterized by the activation of anti-apoptotic proteins, for example decreased BNIP3 and elevated XIAP in human gastric adenocarcinoma, which interact with apoptotic and/or anti-apoptotic molecules in human gastric adenocarcinoma." (PMID 24527069, 2014).
hair follicle tumours (1 paper, 2014). "The expression levels and staining intensity of BNIP3, CAIX, GLUT1, Hif1α, pAKT, PHD2, pmTOR, pS6 and VEGF-A in hair follicle tumours." (PMID 25181405, 2014).
hyperandrogenism (1 paper, 2018). Excessive secretion of androgens from the adrenal glands or gonads. "The decreased expression of BNIP3 in GCs from PCOS women probably results in excessive synthesis of lipid, which provides precursors for the biosynthesis of androgen in follicles, thus participating in hyperandrogenism." (PMID 29344314, 2018).
hyperlipemia (1 paper, 2020). "Subsequently, Bnip3-related mitophagy attenuated oxidative stress and sustained mitochondrial function in the setting of hyperlipemia." (PMID 32923443, 2020). "The interlinked signaling pathways of Bnip3-related mitophagy in response to resveratrol treatment would offer new targets for therapeutic approaches of endothelial protection in the setting of hyperlipemia." (PMID 32923443, 2020).
intracerebral hemorrhage (1 paper, 2022). A cerebrovascular disorder characterized by bleeding into one or both cerebral hemispheres including the basal ganglia and the cerebral cortex. "In addition, the BNIP3 expression is elevated in rats after SCI, and electroacupuncture at GV20-GB7 reduced BNIP3 after intracerebral hemorrhage." (PMID 35462893, 2022).
iron deficiency (1 paper, 2018). "Lastly, we report differences in the expression pattern of markers for BNIP3 and BNIP3L-mediated mitophagy in COPD patients suffering from either iron deficiency or systemic inflammation." (PMID 30302028, 2018). "In conclusion, iron deficiency results in differential expression of BNIP3 and BNIP3L-related mitophagy markers, but does not seem to result in increased overall mitophagy in ID-COPD in our study population." (PMID 30302028, 2018).
ischemic cardiomyopathy (1 paper, 2015). Ischemic cardiomyopathy is a cardiomyopathy in which a weakness in the muscle of the heart due to inadequate oxygen delivery to the myocardium with coronary artery disease being the most common cause. "Since hypoxia can induce a switch from apoptosis to cell survival via alternative splicing of the Bnip3 gene, further studies are required to determine how the splicing of Bnip3 mRNA switches between these two isoforms during non-ischemic and ischemic cardiomyopathy." (PMID 26580598, 2015).
kidney damage (1 paper, 2024). "Moreover, the absence of Bcl-2/adenovirus E1B 19kDa interacting protein 3 (BNIP3) significantly reduces the level of mitochondrial autophagy and markedly exacerbates apoptosis and kidney damage, indicating that BNIP3-mediated mitochondrial autophagy plays a protective role in CI-AKI." (PMID 39655278, 2024).
lactic acidosis (1 paper, 2022). Metabolic acidosis characterized by the accumulation of lactate in the body. "Lactic acidosis secondary to increased LDH activity translocates BNIP3 into the mitochondrial membrane, thereby the mitochondrial permeability transition pore opens." (PMID 36481816, 2022).
lymphoma (1 paper, 2018). A malignant (clonal) proliferation of B- lymphocytes or T- lymphocytes which involves the lymph nodes, bone marrow and/or extranodal sites. "One of the well-established targets of HIF1α is BNIP3 (Bcl-2 [B-cell Leukaemia/Lymphoma 2]/Adenovirus E1B1] Nineteen kD Interacting Protein 3)." (PMID 29707136, 2018).
lysosomal disorders (1 paper, 2025). "High glucose induces mitochondrial–lysosomal disorders in the skeletal system, promotes the abnormal expression of BECN1, LC3II, BCL2 interacting protein 3 (BNIP3), destroys the ubiquitin‐proteasome system and promotes Sirtuin1(Sirt1)/NF‐κB/NLRP3‐induced musculoskeletal injury." (PMID 40853781, 2025).
measles (1 paper, 2018). A highly contagious viral infection caused by the measles virus. "It was done by inserting BNiP3, a pro-apoptotic gene, in measles viral genome to generate an armed oncolytic virus." (PMID 30697531, 2018).
metastatic tumors (1 paper, 2025). "In metastatic tumors, pathway and TF analyses revealed strong hypoxia-inducible factor-1α–driven hypoxia activation, influencing glycolysis (SLC2A1, SLC2A3, PGK1, PDK1, PGM1, and ALDOA), angiogenesis (ANGPTL4 and ADM), and survival in low oxygen (BNIP3, BNIP3L, and NDRG1)." (PMID 40736012, 2025).
mtDNA depletion syndrome (1 paper, 2023). "We propose that the dysregulation of NIX and BNIP3 turnover causes excessive basal mitophagy in FBXL4‐associated mtDNA depletion syndrome." (PMID 37161784, 2023). "Steady‐state ubiquitylation and turnover of NIX and BNIP3 limits basal mitophagy and is dysregulated in MTDPS13, accounting for the elevated mitophagy associated with this encephalopathic mtDNA depletion syndrome." (PMID 37161784, 2023). "Our results suggest that the increased basal mitophagy and associated molecular phenotypes in FBXL4‐associated mtDNA depletion syndrome are caused by NIX and BNIP3 hyperaccumulation." (PMID 37161784, 2023).
nonalcoholic fatty liver (1 paper, 2020). "In the nonalcoholic fatty liver model, the Bnip3 signaling played a key role in alleviating mitochondrial injury and promoting mitophagy." (PMID 32679664, 2020).
nonalcoholic steatohepatitis (1 paper, 2023). "However, this BNIP3-dependent tumor suppression mechanism may be relevant only in the liver, where lipid accumulation promotes both nonalcoholic fatty liver disease (NAFLD) and nonalcoholic steatohepatitis (NASH), which are precursor diseases to HCC." (PMID 37627128, 2023).
oral carcinoma (1 paper, 2025). "However, whether and how BNIP3/‐L‐driven mitophagy promotes the progression and survival of oral carcinoma CSCs under hypoxia remains to be elucidated." (PMID 39945227, 2025).
pelvic organ prolapse (1 paper, 2017). Abnormal descent of a pelvic organ resulting in the protrusion of the organ beyond its normal anatomical confines. "The expressions of HIF-1α and BNIP3 in the uterosacral ligaments were significantly higher in patients with pelvic organ prolapse than in control group." (PMID 29230415, 2017).
squamous cell carcinoma (1 paper, 2023). A carcinoma arising from squamous epithelial cells. "Interestingly, the expression of some of those genes (TGM2, BNIP3, FIS1) has been linked as prognostic markers in squamous cell carcinomas." (PMID 38201216, 2023).
tendinopathy (1 paper, 2024). "Recently, the hypoxia-associated apoptotic gene BNIP3 has been linked to tendinopathy." (PMID 38247510, 2024). "The manipulation of BNIP3 expression following HIF-1α upregulation may be a potential treatment for tendinopathy." (PMID 38247510, 2024).
thyroid tumor (1 paper, 2023). A benign or malignant neoplasm affecting the thyroid gland. "After 48 h, both in breast and thyroid tumor cells, there is an evident reduction in the expression of BNIP3 after treatment with MC3138." (PMID 37627630, 2023).
tongue tumors (1 paper, 2015). "Immunoblotting using lysates derived from these tumors showed that Bnip3 and Hif-1α were marginally elevated in several Sabutoclax-treated tongue tumors." (PMID 26009874, 2015).
ventricular dilation (1 paper, 2020). "In mice lacking NIX, but not BNIP3, cardiac enlargement with decreased left ventricular dilation was observed at 60 weeks." (PMID 32420530, 2020).
ZIKV infection (1 paper, 2023). "ZIKV infection upregulated mitochondrial expression levels of BNIP3, NIX, and PINK1." (PMID 37781396, 2023).